GPX4 (glutathione peroxidase 4)
Diseases named in the same sentence as GPX4 in open-access papers (continued):
Sharing a sentence is not in itself a finding about the gene and the disease.
triple-negative breast carcinoma (40 papers, 2021 to 2026). An invasive breast carcinoma which is negative for expression of estrogen receptor (ER), progesterone receptor (PR), and human epidermal growth factor receptor 2 (HER2). "In patients with triple-negative breast cancer, higher GPX4 expression is associated with lower cytolytic scores and poorer prognoses in immunotherapy cohorts." (PMID 38844964, 2024). "In vivo experiments of triple negative breast cancer showed that inhibition of GPX4 enhanced the anticancer effect of gefitinib through promoting ferroptosis." (PMID 41541703, 2026). "To address this, we cultured triple-negative breast cancer cell lines with GPX4 inhibitors to generate cell lines (M231, 4T1) that were resistant to GPX4 inhibitors (GPX4i)." (PMID 41704007, 2026). "In a PDX model of triple-negative breast cancer, application of the GPX4 inhibitor ML162 in combination with anti-PD-1 therapy increased the patient complete remission rate from 15% to 65%." (PMID 40191204, 2025). "Lnc HCP5-132aa regulates GPX4 and suppresses ROS levels, inhibiting ferroptosis in triple-negative breast cancer." (PMID 40191204, 2025). "Magnetic composite nanoparticles loaded with doxorubicin and DHA synergize to suppress triple-negative breast cancer via the PI3K/AKT/mTOR/GPX4 axis." (PMID 39935430, 2025). "In triple-negative breast cancer, NETs contribute to GPX4-mediated resistance to ferroptosis, possibly acting as a negative feedback mechanism to inhibit ferroptosis of neutrophils surrounding tumor cells through the propagation of ferroptosis." (PMID 40285867, 2025). "DMOCPTL, a derivative of natural product parthenolide, has also been shown to induce GPX4 ubiquitination and reduce GPX4 protein levels, thereby promoting ferroptosis in triple-negative breast cancer cells." (PMID 39856053, 2025). "By downregulating GPX4 expression in tumor tissue and releasing a large amount of iron ions, ferroptosis was induced, resulting in the killing of triple-negative breast cancer." (PMID 39507754, 2024). "Ferroptosis is particularly significant in the luminal androgen receptor (LAR) subtype of triple-negative breast cancer, where GPX4 inhibitors combined with immunotherapy hold potential as a novel treatment strategy." (PMID 39664391, 2024). "Anomanolide C (AC) reduces the expression of GPX4 through ubiquitination and inhibits triple-negative breast cancer (TNBC) proliferation and metastasis both in vitro and in vivo." (PMID 38738174, 2024). "Another study showed that a bartoldine derivative, DMMOCPTL, binds directly to selenosecysteine 46 of GPX4, resulting in ubiquitination of GPX4 in triple-negative breast cancer cells." (PMID 36105219, 2022). "Recently, PTL was linked to ferroptosis in triple-negative breast cancer cells (TNBC) through ROS elevation and ubiquitination of GPx4." (PMID 36591540, 2022). "It has been reported in other models that GPX4 can be degraded via the ubiquitin–proteasome system, as shown in triple-negative breast cancer." (PMID 36291834, 2022). "Later, another study showed that a Parthenolide (PTL)-derived drug DMOCPTL directly bound to the GPX4 active site (selenocysteine 46), and led to GPX4 ubiquitination in triple-negative breast cancer cells." (PMID 35647032, 2022). "Similarly, targeting GPX4 in human triple-negative breast cancer has been shown to enhance the efficacy of anti-PDCD1 therapy." (PMID 38844964, 2024). "Moreover, combining GPX4 inhibitors with anti-PD1 has been found to effectively induce ferroptosis in triple-negative breast cancer, demonstrating superior therapeutic efficacy compared with monotherapy." (PMID 39281833, 2024). "GPx4-mediated ferroptosis is promising for gefitinib resistance in triple-negative breast cancer." (PMID 36768241, 2023).
triple-negative breast carcinoma (continued). "Nanocatalytic activity leads to simultaneous inhibition of GPX4/GSH and FSP1/coq10h2 pathways and synergizes with the GPX4 inactivation function of RSL3 to cause significant ferroptosis damage and thus inhibit malignant progression of triple-negative breast cancer." (PMID 35958626, 2022). "This study aims to determine whether FO/Se modulates G-protein-coupled polyunsaturated fatty acid receptors (GPR-40 and GPR-120) and selenoproteins (Sel-H, Sel-W, and GPx4), and increases the therapeutic effect of doxorubicin in a dose-dependent manner on triple-negative breast cancer (TNBC) mouse." (PMID 36483592, 2022). "Meanwhile, copper oxidizes GSH to oxidized GSH (GSSG) and interacts with the GPX4 inactivation function of RSL3, significantly inducing ferroptosis in triple-negative breast cancer." (PMID 38844964, 2024). "Similarly, in triple-negative breast cancer (TNBC), high GPX4 expression mediates ferroptosis resistance, and the use of GPX4 inhibitors effectively induces ferroptosis and exerts significant antitumor effects." (PMID 41479924, 2025). "Their exosomal microsomal triglyceride transfer protein (MTTP) upregulates GPX4 and XCT to inhibit ferroptosis in colorectal cancer, while adipocyte-secreted oleic acid attenuates lipid peroxidation and ferroptosis in triple-negative breast cancer cells in an ACSL3-dependent manner." (PMID 40285867, 2025). "Furthermore, triple-negative breast cancer emerges as an ideal target for ferroptosis induction therapy due to unique metabolic traits: aberrant PUFA accumulation, elevated labile iron pool, and impaired GPX4-GSH defense." (PMID 40892295, 2025). "Furthermore, in the triple-negative breast cancer cell line BT549, long-chain acyl-CoA synthetase 1(ACSL1) mediates the synthesis of α-tocopherol succinate (αESA, a representative polyunsaturated fatty acid) and induces ferroptosis in BT549 cells, which cannot be suppressed by GPX4 interference." (PMID 39664391, 2024).
lung adenocarcinoma (39 papers, 2019 to 2026). A carcinoma that arises from the lung and is characterized by the presence of malignant glandular epithelial cells. "Further research is needed to understand the role of GPX4 in tumorigenesis and the underlying mechanism responsible for survival outcomes in patients with resected lung adenocarcinoma." (PMID 36443446, 2022). "In conclusions, IHC analysis revealed that GPX4 expression was associated with poor survival outcomes in patients with resected lung adenocarcinoma." (PMID 36443446, 2022). "A decrease in the expression of NRF2, xCT, and GPX4 synergistically enhances lipid peroxidation and ferroptosis in lung adenocarcinoma cells." (PMID 40427585, 2025). "This study aimed to investigate the combined effect of NBP and p-CA on the induction of ferroptosis in lung adenocarcinoma via the GPX4, xCT, and NRF2 pathways." (PMID 40427585, 2025). "A clinicopathological study of lung adenocarcinoma specimens showed that low GPX4 expression was an independent poor prognostic factor, while high FSP1 expression was associated with significantly better prognosis in terms of RFS." (PMID 39594843, 2024). "A recently identified mediator for ALDH1A1-induced resistance of lung adenocarcinoma cells to tyrosine kinase inhibitors was GPX4 (glutathione peroxidase 4)." (PMID 37298333, 2023). "IGF2BP3 inhibited ferroptosis by binding to m6A methylated mRNA encoding anti-ferroptotic factors, including glutathione peroxidase 4 (GPX4), solute carrier family 3 member 2 (SLC3A2), and ferritin heavy chain H1 (FTH1), in lung adenocarcinoma cells." (PMID 36835633, 2023). "KLF11 inhibits lung adenocarcinoma cell proliferation and promotes chemotherapy sensitivity by repressing transcription of GPX4 and promoting ferroptosis." (PMID 37248295, 2023). "Intriguingly, reversion to GPX4 expression significantly attenuated the toxic response of KLF11-promoted chemotherapy to lung adenocarcinoma cells." (PMID 37248295, 2023). "And by targeting GPX4 can induce ferroptosis in lung adenocarcinoma cells and reverse their resistance to epidermal growth factor receptor-tyrosine kinase inhibitor (EGFR-TKI)." (PMID 37005430, 2023). "GPX4 expression was associated with poor OS and DFS, especially in lung adenocarcinoma (p = 0.008, and 0.027, respectively)." (PMID 36443446, 2022). "The GPX4 inhibitor RSL3 has the same effect as the up regulation of miR-324-3p in lung adenocarcinoma cells." (PMID 36408273, 2022). "Cisplatin is an inducer of ferroptosis and apoptosis in lung adenocarcinoma cells, and its mechanism is to cause reduced GSH consumption and GPX4 inactivation." (PMID 34869391, 2021). "It is also observed that overexpression of lncRNA LINC00336 limits ferroptosis induced by GPX4-inhibitor RSL3 in lung adenocarcinoma cells." (PMID 34869391, 2021). "Our data confirmed that ACSL4 expression positively regulated response to oxidative stress pathway in lung adenocarcinoma and negatively correlated with GPX4 in ferroptotic cell death signaling pathways." (PMID 34053456, 2021). "Interestingly, co-treatment significantly reduced GPX4 intensity in both lung adenocarcinoma cell lines." (PMID 40427585, 2025). "On the other hand, low expression of both GPX4 and FSP1 was associated with poor prognosis in lung squamous cell carcinoma, whereas low expression of GPX4 alone was associated with poor prognosis in lung adenocarcinoma." (PMID 39594843, 2024). "In this study, we demonstrated that factors related to ferroptosis can be biomarkers for the prognosis of lung adenocarcinoma and provided the basis for a new therapeutic strategy using ferroptosis induction by regulating GPX4 and FSP1 in lung adenocarcinoma cells." (PMID 39594843, 2024). "However, in this study, the group with high GPX4 expression in lung adenocarcinoma specimens had a better prognosis in terms of both OS and RFS." (PMID 39594843, 2024).
lung adenocarcinoma (continued). "Therefore, miR-324-3p/GPX4 axis can be used as a good target to increase cisplatin sensitivity of lung adenocarcinoma cells." (PMID 36408273, 2022). "It was found that miR-324-3p could directly act on GPX4 and inhibit its expression, while overexpression of GPX4 reversed the cisplatin sensitization effect of miR-324-3p on lung adenocarcinoma cells." (PMID 36408273, 2022). "As reported, CREB can suppress lipid peroxidation by binding to the promoter region of glutathione peroxidase 4 (GPX4), suggesting that CREB upregulates the transcriptional level of GPX4 and inhibits the ferroptosis pathway in lung adenocarcinoma." (PMID 40328750, 2025). "For lung adenocarcinoma, KLF13 induced ferroptosis via repressing transcription of GPX4, thus sensitizing lung adenocarcinoma cells to chemotherapy drugs." (PMID 41410190, 2025). "For instance, Hedyotis diffusa injection (HDI) has been found to induce ferroptosis in lung adenocarcinoma cells by increasing ROS release through the Bax/Bcl2/VDAC2/3 axis, independently of GPX4 and the PUFA-PLS pathway." (PMID 39944353, 2024). "First, to assess the potential of GPX4 and FSP1 as therapeutic targets, cell death rates of lung adenocarcinoma cells treated with GPX4 inhibitors (RSL3 and ML210) and FSP1 inhibitor (iFSP1) alone or in combination were determined." (PMID 39594843, 2024). "Fifth, the present study did not allow for a detailed examination of the expression levels of GPX4 and FSP1 per cell in lung adenocarcinoma tissue." (PMID 39594843, 2024). "Here, we report that KLF11 inhibits lung adenocarcinoma (LUAD) cell proliferation and promotes chemotherapy sensitivity by participating in the GPX4-related ferroptosis pathway." (PMID 37248295, 2023). "In brain metastasis of lung adenocarcinoma, Glutathione S‐transferase M1 (GSTM1) is another protein that is stablized by GPX4 and concurrently result in inhibition of ferroptosis and subsequent resistance to platinum through increasing GSH consumption." (PMID 34926310, 2021). "In summary, we found that erlotinib-resistant lung adenocarcinoma cells depended on ALDH1A1 and that ALDH1A1 conferred EMT and drug resistance by facilitating the ROS-RCS metabolic pathway and by activating GPX4 and SOD2 transcription." (PMID 31695757, 2019). "Our in silico analysis of single-cell sequencing data from human breast and lung adenocarcinoma tumors as well as from human pancreatic normal tissue further revealed the existence of distinct subpopulations, which feature either high LDHB or GPX4 expression but rarely both together." (PMID 40090955, 2025). "While GPX4 is central to protecting a variety of cells from ferroptosis, in lung adenocarcinoma cells, GPX4 deletion is not sufficient to induce ferroptosis." (PMID 33824345, 2021). "Therefore, we examined whether ferroptosis could be induced by depleting GPX4 and FSP1 in lung adenocarcinoma cells." (PMID 39594843, 2024). "Importantly, survival in lung adenocarcinoma (LUAD) did not significantly segregate by GPX4, TXNRD1 or combined GPX4 and TXNRD1 expression suggesting a function for redox pathway plasticity in determining patient outcome to be a unique feature of SCLC." (PMID 33824345, 2021). "Among lung adenocarcinoma cells, A549 and ABC-1 cells are cells with relatively lower GPX4 expression than other lung adenocarcinoma cells such as VMRC-LCD and RERF-LC-MS cells, which may be relatively well suited to deplete GPX4 and FSP1 and induce ferroptosis." (PMID 39594843, 2024). "IGF2BP3 could stabilize a spectrum of anti-ferroptosis mRNA, including glutathione peroxidase 4 (GPX4), solute carrier family 3 member 2 (SLC3A2), acyl-CoA synthetase long chain family member 3 (ACSL3), and ferritin heavy chain 1 (FTH1), to inhibit ferroptosis in lung adenocarcinoma cells." (PMID 37554271, 2023).
lung adenocarcinoma (continued). "By analyzing the expression levels of glutathione peroxidase 4 (GPX4), ferroptosis suppressor protein 1 (FSP1), and 4-Hydroxy-2-nonenal (4-HNE) in resected lung adenocarcinoma tissues, the study seeks to establish a relationship with clinicopathological factors and patient outcomes." (PMID 39594843, 2024).
prostate carcinoma (36 papers, 2014 to 2026). A carcinoma that arises from epithelial cells of the prostate gland. "GPX4 showed significantly higher expression in prostate cancer (P < 0.05) and was associated with infiltrating immunocytes." (PMID 38705987, 2024). "On the other hand, SNP (rs3746165) in GPx4 is linked to the risk of lethal prostate cancer." (PMID 35208621, 2022). "And rs3746165 variants in GPx4 may be associated with risk of lethal prostate cancer." (PMID 28499373, 2017). "In this study, we utilize our established enzalutamide-resistant prostate cancer cell lines to reveal a vulnerability of these cancer cells to GPX4-targeted ferroptosis." (PMID 42215431, 2026). "In summary, our results illustrate that evodiamine exerts potent antitumor effects against prostate cancer through promoting TRIM26-mediated degradation of GPX4 protein and triggering ferroptosis." (PMID 40420092, 2025). "Our results suggest that proteasomal degradation pathway is essential for regulating GPX4 protein stability in prostate cancer cells." (PMID 40420092, 2025). "This study demonstrates that evodiamine exerts potent antitumor effects against prostate cancer through inhibiting TRIM26-mediated stabilization of GPX4 protein and triggering ferroptosis." (PMID 40420092, 2025). "To gain deeper insights into the role of TRIM26, we overexpressed it in prostate cancer cells and subsequently evaluated its influence on evodiamine-induced inhibition of GPX4 protein expression." (PMID 40420092, 2025). "In summary, our findings suggest that GRh2 exposure induces ferroptosis in prostate cancer cells by repressing the SLC7A11/GPX4 pathway, leading to decreased cell viability." (PMID 40919139, 2025). "These in vivo findings suggest that evodiamine can inhibit prostate cancer tumor growth through the TRIM26/GPX4 signaling pathway." (PMID 40420092, 2025). "The AGPS degradation-induced enrichment of membrane polyunsaturated fatty acids (PUFAs) synergizes with ML210-mediated GPX4 inhibition, significantly enhancing ferroptosis in prostate cancer cells." (PMID 40427071, 2025). "Given that evodiamine can induce ferroptosis in prostate cancer cells in vitro through the TRIM26/GPX4 signaling axis, we evaluated its effects on prostate cancer tumor growth in vivo." (PMID 40420092, 2025). "Consistent with previous findings, we discovered that evodiamine can inhibit GPX4 protein expression in prostate cancer cells." (PMID 40420092, 2025). "We found that evodiamine induced prostate cancer cells ferroptosis mainly depending on suppressing the stability of the GPX4 protein." (PMID 40420092, 2025). "The phosphorylation of CREB promotes GPX4 transcription, inhibiting ferroptosis and conferring prostate cancer cells with resistance to androgen receptor antagonists." (PMID 38726001, 2024). "We further explored the clinical relationship between GPX4 and prostate cancer using The Cancer Genome Atlas (TCGA) database." (PMID 38705987, 2024). "We loaded the GPX-4 inhibitor RSL3 into RMPs to investigate the potential for a synergistic effect of GPX-4 inhibition and RMPs on ferroptosis to treat prostate cancer." (PMID 38705987, 2024). "The results of this study showed that FBI-1 inhibited the ferroptosis of prostate carcinoma PC-3 cells (a typical endocrine-independent prostate carcinoma cell line) via the miR-324-3p/glutathione peroxidase 4 (miR-324-3p/GPX4) axis." (PMID 38947389, 2024). "SLC7A11 and GPX4 are two key molecules that inhibit ferroptosis, and are highly expressed in prostate cancer and CRPC." (PMID 38705987, 2024). "We investigated the expression of the GPX4 gene in different cancers, and found that GPX4 was highly expressed in the majority of moderate cancers, including prostate cancer." (PMID 38705987, 2024).